ABHD17C (abhydrolase domain containing 17C, depalmitoylase)
Description:
Hydrolyzes fatty acids from S-acylated cysteine residues in proteins. Has depalmitoylating activity towards NRAS and DLG4/PSD95.
Synonyms: FAM108C1
Tractability: Antibody: its Gene Ontology location is reachable by antibodies, with high confidence. PROTAC: ubiquitination databases record sites on it; its protein half-life has been measured.
Gene: Protein-coding gene on chromosome 15 (80,679,684 to 80,755,621, forward strand). Ensembl gene ENSG00000136379.
Subcellular location: Recycling endosome membrane; Cell projection, dendritic spine; Postsynaptic density membrane
Pathways (Reactome):
Signal Transduction: RAS processing
Gene Ontology:
Molecular function: palmitoyl-(protein) hydrolase activity; protein binding
Biological process: protein depalmitoylation; negative regulation of protein localization to microtubule; positive regulation of protein localization to endosome; regulation of postsynapse organization
Cellular component: endosome membrane; plasma membrane; postsynaptic density membrane; recycling endosome membrane; dendritic spine; glutamatergic synapse; postsynaptic density
Genetic constraint (gnomAD): Loss-of-function variants: 11 observed, 19.8 expected, observed/expected ratio (o/e) 0.56, 90% interval 0.35 to 0.92. The synonymous counts are far from expectation, so gnomAD's model fits this gene poorly and the ratio says little. Missense variants: 260 observed, 368.46 expected, observed/expected ratio (o/e) 0.71, 90% interval 0.64 to 0.78. Synonymous variants: 222 observed, 164.01 expected, observed/expected ratio (o/e) 1.35, 90% interval 1.21 to 1.51.
Homologues: Orthologues: dog ABHD17C (96% identical), mouse Abhd17c (94% identical), rat Abhd17c (94% identical), guinea pig ABHD17C (91% identical), chimpanzee ABHD17C (86% identical), tropical clawed frog abhd17c (86% identical), Caenorhabditis elegans F01D5.8 (36% identical), Caenorhabditis elegans F01D5.7 (33% identical). Paralogues in human: ABHD17A (72% identical), ABHD17B (68% identical), ABHD12 (22% identical), ABHD12B (20% identical), ABHD13 (18% identical), ABHD16A (16% identical), ABHD16B (14% identical).
Diseases named in the same sentence as ABHD17C in open-access papers:
ABHD17C is named in the same sentence as 6 diseases in open-access papers, as found by Europe PMC text mining. Sharing a sentence is not in itself a finding about the gene and the disease. The quoted sentences say what the papers report.
breast carcinoma (2 papers, 2019 to 2025). "The low expression of HSD17B11 and ITGA2 and the high expression of VIM and ABHD17C have all been validated by recent sequencing studies on breast cancer, reflecting the accuracy of these two rules." (PMID 31456818, 2019).
hepatocellular carcinoma (1 paper, 2023). A malignant tumor that arises from hepatocytes. "We previously showed that ABHD17C has oncogenic roles in hepatocellular carcinoma (HCC) cells, and its mRNA stability is controlled by miR-145-5p." (PMID 37993419, 2023).
oral cancer (1 paper, 2024). "In addition, several downstream targets of these specific microRNAs were upregulated by all oral cancer cell lines, such as MBTD1 and FSCN1, or downregulated in all cell lines, such as CLCN3, FLI-1, MRTFB, DAB, SRGAP1, and ABHD17C." (PMID 38396844, 2024).
pancreatic cancer (1 paper, 2023). "Subsequently, ECAR and OCR experiments, which represent the potential storage capacity and maximum storage capacity of glycolysis, demonstrated that the overexpression of ABHD17C increased the glycolysis level of pancreatic cancer cells." (PMID 37273016, 2023). "Based on these results, we concluded that MDSCs are bone marrow-derived cells that typically exert immunosuppressive functions, and an increase in the proportion of MDSCs due to ABHD17C overexpression leads to the formation of an immunosuppressive microenvironment in pancreatic cancer." (PMID 37273016, 2023).
cancer (6 papers, 2012 to 2025). A tumor composed of atypical neoplastic, often pleomorphic cells that invade other tissues. "Analysis of the Cancer Therapeutics Response Portal (CTRP) revealed that ABHD17C expression was significantly correlated with cellular resistance against ferroptosis inducers, including RSL3, ML210, and ML162, suggesting that ABHD17C might function as a ferroptosis suppressor." (PMID 40569151, 2025). "Our results showed that high expression of ABHD17C in malignant ductal cells was positively correlated with metabolic processes and could be enriched in cancer-related signaling pathways such as MAPK signaling pathway, protein glycosylation, Wnt signaling pathway, and PI3K-Akt signaling pathway." (PMID 37273016, 2023). "Notably, two specific genes, ZDHHC9 (a palmitoyl-acyltransferase) and ABHD17C (a de-palmitoyl-acyltransferase), displayed significant dysregulation across more than 10 human cancer types and exhibited correlation with cancer subtypes in seven human cancer types." (PMID 37978524, 2023).
tumor (2 papers, 2025 to 2026). "Alpha/beta hydrolase domain-containing protein 17C (ABHD17C) is a kind of depalmitoyltransferase and its roles in tumor immunology remain largely unclear." (PMID 42154583, 2026). "Therefore, this study elucidates the mechanism by which the depalmitoyltransferase ABHD17C protects tumor cells from macrophage phagocytosis, which highlights the therapeutic potential of targeting the ABHD17C/BCL6B/CD24 signaling axis by macrophage-mediated innate immune pathway in PC." (PMID 42154583, 2026).